DCDC2 (doublecortin domain containing 2)
Description:
Protein that plays a role in the inhibition of canonical Wnt signaling pathway. May be involved in neuronal migration during development of the cerebral neocortex (By similarity). Involved in the control of ciliogenesis and ciliary length.
Synonyms: KIAA1154; RU2; DCDC2A; NPHP19; DFNB66; NSC; RU2S
Tractability: Small molecule: it has a binding pocket of medium quality.
Gene: Protein-coding gene on chromosome 6 (24,171,755 to 24,360,249, reverse strand). Ensembl gene ENSG00000146038.
Subcellular location: Cell projection, cilium; Cytoplasm, cytoskeleton, cilium axoneme; Cell projection, kinocilium; Cytoplasm, cytoskeleton
Subcellular location (Human Protein Atlas): Cytosol; Microtubules; Acrosome; Centriolar satellite; Equatorial segment; Mitotic spindle; Principal piece
Gene Ontology:
Molecular function: protein binding; kinesin binding
Biological process: cilium assembly; positive regulation of smoothened signaling pathway; regulation of cilium assembly; regulation of Wnt signaling pathway; sensory perception of sound; cellular defense response; neuron migration; intracellular signal transduction
Cellular component: axoneme; cilium; cytoplasm; mitotic spindle; kinocilium; microtubule; microtubule organizing center; cytoskeleton
Genetic constraint (gnomAD): Loss-of-function variants: 33 observed, 41.55 expected, observed/expected ratio (o/e) 0.79, 90% interval 0.6 to 1.06. The upper end of that interval is the gene's LOEUF score, 1.06, which puts it in group 4 of 6, group 1 being the genes least tolerant of losing a copy. Missense variants: 511 observed, 548.45 expected, observed/expected ratio (o/e) 0.93, 90% interval 0.87 to 1. Synonymous variants: 212 observed, 204.33 expected, observed/expected ratio (o/e) 1.04, 90% interval 0.93 to 1.16.
Gene-disease validity (ClinGen):
ClinGen rates the evidence that DCDC2 causes each of these diseases.
ciliopathy (autosomal recessive): Definitive. A genetic disorder of the cellular cilia or the cilia anchoring structures, the basal bodies, or of ciliary function.
nonsyndromic genetic hearing loss (autosomal recessive): Limited.
Homologues: Orthologues: chimpanzee DCDC2 (99% identical), macaque DCDC2 (95% identical), pig DCDC2 (88% identical), rabbit DCDC2 (87% identical), dog DCDC2 (84% identical), guinea pig DCDC2 (84% identical), mouse Dcdc2a (83% identical), rat Dcdc2 (83% identical), tropical clawed frog dcdc2 (52% identical). Paralogues in human: DCDC2B (27% identical), DCDC2C (25% identical).
Diseases named in the same sentence as DCDC2 in open-access papers:
DCDC2 is named in the same sentence as 49 diseases in open-access papers, as found by Europe PMC text mining. Sharing a sentence is not in itself a finding about the gene and the disease. The quoted sentences say what the papers report.
dyslexia (64 papers, 2007 to 2025). A learning disorder characterized by an impairment in processing written words. "At the molecular level, dyslexia has been associated with genetic variations such as DCDC2, KIAA0319, and ROBO1, which affect neuronal migration and cortical layering." (PMID 40941656, 2025). "According to a recent meta-analysis, the C allele of the rs807701 polymorphism of the DCDC2 gene can increase the risk of dyslexia." (PMID 37667328, 2023). "In humans, DCDC2 has been associated with dyslexia risk and abnormal white matter integrity [reduced fractional anisotropy (FA)] in both the arcuate fasciculus (connecting Broca and Wernicke's areas) and the corpus callosum." (PMID 38234592, 2023). "Researchers found that schizophrenic patients have a dyslexia-related risk gene DCDC2 (doublecortin domain-containing protein 2), and their volume of brain regions related to reading is significantly decreased." (PMID 35911987, 2022). "shRNAi-mediated knockdown of the homolog of the dyslexia risk gene DCDC2 in the rat resulted in impaired speech sound discrimination without abnormal responses to sound in the primary auditory cortex." (PMID 36452335, 2022). "Briefly, more than nine loci have been identified as candidates for susceptibility to SLD, with several genes, particularly DYX1C1, ROBO1, KIAA0319, and DCDC2, repeatedly linked to the disorder and/or measures of reading processes disturbed in dyslexia." (PMID 34068951, 2021). "GWAS have found suggestive evidence for DCDC2 in dyslexia susceptibility in a study that investigated the genetics of mathematical and reading disability." (PMID 30218584, 2018). "Similar results have been found in experiments targeting homologs of the other main dyslexia susceptibility genes, Dyx1c1, Dcdc2, and Robo1." (PMID 29045729, 2017). "Deletion of Dcdc2, another dyslexia susceptibility candidate gene, has recently been shown to affect cortical activity by altering the temporal firing pattern and functional connectivity in the neocortex." (PMID 27510895, 2017). "Recent reports have described mutations in the dyslexia candidate gene DCDC2 in individuals with renal-hepatic ciliopathy or recessive deafness." (PMID 26400686, 2015). "In the past decade, a number of candidate dyslexia susceptibility genes (CDSGs) have been identified, three of which have garnered significant support in diverse populations, including DCDC2 and KIAA0319 on Chromosome (Chr) 6p22.2 and DYX1C1 on Chr 15q21." (PMID 23724130, 2013). "A number of candidate dyslexia susceptibility genes have been identified, including DCDC2 and KIAA0319 on Chromosome (Chr) 6p22.2 and DYX1C1 on Chr 15q21." (PMID 23724130, 2013). "Genetic studies in humans have led to the identification of several other candidate genes for dyslexia, among which DCDC2, KIAA0319 and ROBO1 have been strongly implicated in either neuronal migration in the developing cortex or axon and dendritic guidance." (PMID 23650548, 2013). "Doublecortin domain containing 2, DCDC2, has been suggested to play a causative role in reading disabilities and has been implicated as a susceptibility gene for Dyslexia." (PMID 24705084, 2012). "Disruption of several genes associated with dyslexia, including Dcdc2, impairs the migration of developing neurons from the ventricular zone to their proper location in the cortical plate." (PMID 21698230, 2011). "Genetic studies have identified several variants within or near the Doublecortin domain containing 2 (DCDC2) gene that are associated to dyslexia." (PMID 21698230, 2011). "Targeted sequencing of two genes in the dyslexia-risk locus DYX2 on chromosome 6 implicate a haplotype that stretches 211kb from the downstream region of KIAA0319 to the second intron of DCDC2 and is associated with reduced performance on timed real-word reading adjusted for VIQ." (PMID 40424442, 2025).
dyslexia (continued). "DCDC2 was originally identified in a linkage region for dyslexia susceptibility, and SNPs in and near this gene were subsequently associated with dyslexia in candidate gene studies, although some investigations, including a meta-analysis of seven studies, failed to support this." (PMID 35998220, 2022). "In addition, the genetic relation of the DCDC2 variants within the dyslexia phenotype has been found to differ across the subgroup classification of the disorder." (PMID 30379906, 2018). "DCDC2 gene polymorphisms have been associated with dyslexia in Chinese Uyghur children." (PMID 29081827, 2017). "Considering that mutations in doublecortin genes lead to neuronal migration impairment, and RNA knockdown disturbs neuron progenitors migration in rat embryos, it has been suggested that defects in the DCDC2 gene cause dyslexia by means of incorrect migration of neural progenitor cells." (PMID 28125008, 2017). "While its function remains undisclosed, DCDC2 has been shown to be associated with dyslexia." (PMID 28125008, 2017). "Single-nucleotide polymorphisms (SNPs) within DCDC2 showed association with both dyslexia and reading abilities in independent studies, but the functional mechanisms underlying these associations remain unclear." (PMID 28742079, 2017). "Our work was prompted by recent studies that based their hypotheses and research designs on the assumption that the DCDC2 deletion is an established susceptibility factor for dyslexia." (PMID 28742079, 2017). "Disrupted in schizophrenia 1 (Disc1), pericentriolar material 1 (PCM-1), and human jouberin (Abelson helper integration site 1 (AHI1)) are linked with schizophrenia, hamartin (Tuberous sclerosis 1 (TSC1)) is linked with autism, and pericentrin (PCNT), DCDC2, and Dyx1c1 are linked with dyslexia." (PMID 28125008, 2017). "The association between DCDC2 and dyslexia has been supported by several independent studies." (PMID 27100778, 2016). "Finally, carrying two minor alleles of the DCDC2 SNP rs1091047 (a dyslexia gene) was most predictive of control status." (PMID 25880661, 2015). "A cilia-related coexpression module derived from microarray datasets finds that the dyslexia associated genes, doublecortin domain containing 2 (DCDC2), dyslexia susceptibility 1 candidate gene 1 (DYX1C1), and Kazusa Institute AA0319 (KIAA0319) are coexpressed in cilia." (PMID 24275328, 2014). "In support of this, a cilia-related coexpression module derived from publically available microarray datasets found that the dyslexia associated genes, DCDC2, DYX1C1, and KIAA0319 are coexpressed in cilia, suggesting they interact with genes involved in the determination of LR asymmetry." (PMID 24068947, 2013). "In a longitudinal study of a cohort of English children, associations were observed between DCDC2 and dyslexia, and between CMIP and KIAA0319 and single-word reading and spelling across the ability range; significance was increased by inclusion of individuals with comorbid LI or ADHD." (PMID 23308072, 2012). "Several genetic loci in addition to DCDC2 have been linked to dyslexia susceptibility." (PMID 23300604, 2012). "In addition, RNAi downregulation of the dyslexia-susceptibility genes Dcdc2, Kiaa0319 and Dyx1c1 in rat embryos also affects neuronal migration to cortex." (PMID 22426781, 2012). "Association of dyslexia with SNPs in the 5′ UTR of the DCDC2 gene has also been found." (PMID 23308072, 2012). "We show here that DYX1C1 is physically associated with the centrosome and the cilium, and also note that another strong dyslexia candidate gene from human genetic studies, DCDC2, encodes a protein that is a component of the primary cilium that can impact cilia length when overexpressed." (PMID 23300604, 2012). "DCDC2 is one of the candidate susceptibility genes for dyslexia." (PMID 21698230, 2011).
dyslexia (continued). "Dyslexia is one such neurocognitive impairment that has recently been linked to primary cilia through the localization of the product of the candidate dyslexia susceptibility gene Dcdc2 to primary cilia in primary rat neurons, and the effect of its overexpresion on cilia length." (PMID 23300604, 2012). "While this paper presents conceptual connections between electrophysiological antero-posterior asymmetry and dyslexia-related genes, such as DCDC2, KIAA0319, or ROBO1 this is hypothetical and not a fact due to a lack of genetic or molecular data." (PMID 40941656, 2025). "Our analysis identified the 6p22 locus previously implicated in dyslexia, childhood apraxia of speech (CAS), and language impairment, confirming the role of KIAA0319 and DCDC2 in this locus." (PMID 39202429, 2024). "DCDC2, a member of the DCX family, has been identified as a vital candidate susceptibility gene for dyslexia." (PMID 38658618, 2024). "DYX1C1 (DNAAF4) and DCDC2 are two of the most replicated dyslexia candidate genes in genetic studies." (PMID 37237337, 2023). "As it was mentioned before, DCDC2 is an essential gene for developmental Dyslexia, and it is localized to the ciliary axoneme and the mitotic spindle fibres in a cell-cycle-dependent manner." (PMID 34674647, 2021). "Again, no single-marker association reached statistical significance, but pairwise SNP interaction between rs2274305 in DCDC2 and rs4504469 in KIAA0319 showed significant association with dyslexia as well as with dyslexia plus comorbid ADHD." (PMID 34068951, 2021). "This performance is significantly impaired in both populations of dyslexia, being stronger in the one carrying DCDC2 deletion." (PMID 34228165, 2021). "For example, certain polymorphisms in the dyslexia candidate genes DYX1C1, DCDC2, and KIAA0319 correlate with white matter density in the brain of children." (PMID 32445086, 2020). "Rodent models for other dyslexia candidate genes (i.e., Dcdc2 and Dyx1c1) have also suggested an impairment in auditory processing." (PMID 30950042, 2019). "The DYX1C1, DCDC2, ROBO1, and KIAA0319 genes are known as the classical dyslexia susceptibility genes and they are supported by a number of independent replication studies (Carrion‐Castillo, Franke, & Fisher, 2013; Newbury, Monaco, & Paracchini, 2014)." (PMID 30950042, 2019). "The impact of altered gene expression levels on neuronal function was repeatedlyobserved for the best replicated dyslexia candidate genes (DCDC2,DYX1C1 and KIAA0319)." (PMID 29473935, 2018). "Several candidate dyslexia-susceptibility genes, including KIAA0319, DYX1C1, and DCDC2, have been identified in humans." (PMID 27510895, 2017). "An intronic deletion within the DCDC2 gene, with ~8% frequency in European populations, is increasingly used as a marker for dyslexia in neuroimaging and behavioral studies." (PMID 28742079, 2017). "Several dyslexia susceptibility loci and candidate genes have been identified, with DYX1C1, DCDC2, KIAA0319, and ROBO1 established as the main candidates." (PMID 29045729, 2017). "Nevertheless, the DCDC2 deletion is becoming increasingly used in research aimed at identifying the neuronal correlates of dyslexia." (PMID 28742079, 2017). "Several candidate dyslexia susceptibility genes have been identified through linkage analysis and association studies, including DYX1C1, DCDC2, and KIAA0319." (PMID 27510895, 2017). "Previously, SNPs within three dyslexia candidate susceptibility genes (DYX1C1, DCDC2, and KIAA0319) have been shown to be associated with white matter density in the left temporoparietal region." (PMID 27240594, 2017). "With this study, we aimed to investigate the role of the DCDC2 deletion in contributing to dyslexia or measures of reading and component skills." (PMID 28742079, 2017).
dyslexia (continued). "The doublecortin domain-containing 2 (DCDC2) gene, which is located on chromosome 6p22.1, has been widely suggested to be a candidate gene for dyslexia, but its role in typical reading development over time remains to be clarified." (PMID 27100778, 2016). "Recently, doublecortin domain-containing protein 2 (DCDC2), which is located on chromosome 6p22.1, has been widely accepted to be one of the candidate genes for dyslexia." (PMID 27100778, 2016). "In this regard it is interesting to note that increased expression of the dyslexia candidate gene (DCDC2) affects the length and signaling of PNC and hippocampal neuronal morphology." (PMID 24695551, 2014). "The dyslexia candidate gene DCDC2 was recently shown to localize to neuronal cilia upon overexpression and regulate cilia length and signalling." (PMID 23650548, 2013). "The literature mining approach revealed the consensus ciliary signature to include a group of genes related to the neurological disorder dyslexia (DCDC2, DYX1C1 and KIAA0319)." (PMID 22558177, 2012). "The DYX2 locus proved more complex, as it contains two candidate dyslexia susceptibility genes, KIAA0319 in the proximal portion and DCDC2 (doublecortin domain-containing protein 2; MIM 605755) approximately 200 kb distal." (PMID 23308072, 2012). "In a subsequent study the late MMN was associated to rare variants between the prominent dyslexia candidate genes KIAA0319 and DCDC2, both located on chromosome 6." (PMID 22606227, 2012). "We show here that the dyslexia candidate protein DCDC2 localizes to the primary cilium in primary neurons." (PMID 21698230, 2011). "In this study we have investigated the cellular function of the dyslexia candidate protein DCDC2 in neurons." (PMID 21698230, 2011). "We analysed markers, previously reported to be associated with dyslexia, located within the MRPL19/C2ORF3, KIAA0319, DCDC2 and DYX1C1 genes in a sample of 520 individuals and tested them for association with reading and spelling measures." (PMID 20846247, 2011). "Together with two other dyslexia susceptibility candidate genes (dyslexia susceptibility 1 candidate 1, DYX1C1, and KIAA0319), Dcdc2 has been shown to be involved in neuronal migration in the developing cortex in rats." (PMID 21698230, 2011). "We present additional evidence for a role in dyslexia risk for DCDC2, KIAA0319, GRIN2B and CYP19A1, but not for DNAAF4." (PMID 40424442, 2025). "DCDC2 was connected to dyslexia in 2005, however, a recent study indicated that deletion of DCDC2 did not enhance a risk factor for dyslexia." (PMID 37529113, 2023). "For instance, the European consortium NeuroDys performed a cross-linguistic case-control association study of dyslexia with data from more than 950 dyslexic individuals using targeted genotyping of selected markers in DYX1C1, DCDC2, KIAA0319, and the MRPL19/C2orf3 locus." (PMID 34068951, 2021). "Furthermore, targeted knock down of other dyslexia susceptibility candidate genes (such as KIAA0319 and DCDC2) resulted in similar patterns of neuronal migration." (PMID 29081827, 2017). "We also analyzed data from five distinct cohorts, enriched for individuals with dyslexia, and did not identify any signal indicative of associations for the DCDC2 deletion with reading-related measures, including in a combined sample analysis (N=526)." (PMID 28742079, 2017). "In summary, through both a re-evaluation of the published literature and new genetic association analyses, our results show that there is no strong evidence in support of the DCDC2 deletion as a risk factor for dyslexia." (PMID 28742079, 2017). "Taken together, these studies do not support a role of the DCDC2 deletion as a specific risk factor for dyslexia." (PMID 28742079, 2017). "The evidence we have gathered does not support an association between the DCDC2 deletion and dyslexia or quantitative measures of reading abilities." (PMID 28742079, 2017).